U2SURP (U2 snRNP associated SURP domain containing)
Synonyms: SR140; fSAPa
Tractability: PROTAC: UniProt records ubiquitination sites on it; ubiquitination databases record sites on it; its protein half-life has been measured.
Gene: Protein-coding gene on chromosome 3 (142,964,497 to 143,060,725, forward strand). Ensembl gene ENSG00000163714.
Subcellular location: Nucleus
Subcellular location (Human Protein Atlas): Nucleoplasm
Pathways (Reactome):
Metabolism of RNA: mRNA Polyadenylation; mRNA Splicing - Major Pathway
Chromatin organization: CHD1 and CHD2 subfamily
Disease: Dengue Virus-Host Interactions
Gene Ontology:
Molecular function: protein binding; RNA binding; nucleic acid binding
Biological process: RNA processing
Cellular component: nucleoplasm; nucleus; U2 snRNP
Genetic constraint (gnomAD): Loss-of-function variants: 2 observed, 86.78 expected, observed/expected ratio (o/e) 0.023, 90% interval 0.008 to 0.073. The upper end of that interval is the gene's LOEUF score, 0.073, which puts it in group 1 of 6, group 1 being the genes least tolerant of losing a copy. Missense variants: 561 observed, 955.68 expected, observed/expected ratio (o/e) 0.59, 90% interval 0.55 to 0.63. Synonymous variants: 328 observed, 317.67 expected, observed/expected ratio (o/e) 1.03, 90% interval 0.94 to 1.13.
Homologues: Orthologues: chimpanzee U2SURP (99% identical), dog U2SURP (99% identical), pig U2SURP (99% identical), rabbit U2SURP (99% identical), mouse U2surp (99% identical), rat U2surp (99% identical), macaque U2SURP (96% identical), guinea pig U2SURP (89% identical), tropical clawed frog u2surp (84% identical), zebrafish u2surp (72% identical), Drosophila melanogaster CG9346 (43% identical), Caenorhabditis elegans sap-140 (29% identical).
Diseases named in the same sentence as U2SURP in open-access papers:
U2SURP is named in the same sentence as 5 diseases in open-access papers, as found by Europe PMC text mining. Sharing a sentence is not in itself a finding about the gene and the disease. The quoted sentences say what the papers report.
breast carcinoma (1 paper, 2021). "In addition, inhibiting the expression of U2surp (down: 0.575-fold at Ser974) inhibits cell colony formation and significantly slows cell growth in breast cancer cells." (PMID 33897769, 2021).
tumor (2 papers, 2020 to 2022). "Except U2SURP, 12 DEGs were identified in GSE67614.50 tumor tissues from HNSCC radiosensitive patients and 52 from radioresistant HNSCC patients were selected." (PMID 36212151, 2022).
U2SURP also shares sentences with these, for which no sentence is quoted: cancer (2 papers); hepatitis B (1); hepatitis C (1).